CRP (C-reactive protein)
Diseases named in the same sentence as CRP in open-access papers (continued):
Sharing a sentence is not in itself a finding about the gene and the disease.
COVID-19 (continued). "CRP, a protein originated from the liver, was suggested to be elevated in diabetic patients compared to non-diabetic patients during the infection of COVID-19." (PMID 38455656, 2024). "Independent of initial disease severity, having received dexamethasone during acute COVID-19 was associated with higher levels of IL6, IL10, sCD14 and CRP compared to those who did not receive dexamethasone, in multivariable analyses." (PMID 39008486, 2024). "Therefore, it is considered that the values for CRP and LDH were much higher in the COVID-19 cohorts from the years 2020 and 2021 because patients developed the Delta variant of the SARS-CoV−2 virus." (PMID 38392603, 2024). "Another clinical study showed that co-supplementation of curcumin and piperine decreased the levels of CRP and aspartate aminotransferase (AST) and increased hemoglobin levels in COVID-19 intensive care unit patients, showing promise as a supplementary therapy." (PMID 39126050, 2024). "Increased CRP and ESR levels were observed in the COVID-19 patients." (PMID 38398719, 2024). "Our results discovered that blood CRP, LDH, Ferritin, ALP, Bilirubin, and D-Dimer levels were the strongest predictive characteristic of COVID-19 diagnosis, which is consistent with earlier research identifying serum levels as a biomarker of clinical severity and poor prognosis." (PMID 39273719, 2024). "In non-critically ill COVID-19 patients, pneumonia treated with high-dose methylprednisolone showed lower C-reactive protein (CRP), and D-dimer compared to high-dose dexamethasone." (PMID 38350878, 2024). "Not only that, the assessed efficiency of serum transglin was not less than COVID-19 severity scores and was a little higher than those in commonly inflammatory cytokines, such as IL-6 and CRP." (PMID 39676863, 2024). "Importantly, elucidation of putative serum mediators revealed a significant upregulation of key cytokines in COVID-19 positive patients compared to controls, including IL-6, TNF-α, IL-1β, IL-10, and CRP." (PMID 38041432, 2024). "Similarly, all common infection indicators at admission (including serum WBC count, PCT, CRP, IL-6, D-Dimer, and LDH level) in COVID-19 subgroup with secondary infection were great higher than that of patients without bacterial infection (p < 0.05)." (PMID 38246947, 2024). "The clinical picture of patients hospitalized for complications of COVID-19 is usually characterized by blood tests and some biomarkers, such as platelet counts, international normalized ratio (INR), C-reactive protein (CRP), D-dimer, pro-calcitonin (PCT), and serum lactate." (PMID 39504070, 2024). "Patients with HCM and COVID-19 were also noted to have a higher peak CRP when compared to those without prior COVID-19 (Inter-quartile range of 9.0–106.9 v 1.8–21.3, p < 0.01)." (PMID 38667722, 2024). "C-reactive protein (CRP) is a non-specific biomarker for acute inflammatory diseases such as infections (including COVID-19) and for chronic inflammatory conditions such as cardiovascular diseases." (PMID 39485740, 2024). "ALT and AST but not GGT levels increased with COVID-19 disease severity, and hospitalised patients had high CRP levels." (PMID 39408818, 2024). "In our study, pregnant ICU patients with COVID-19 exhibited more severe respiratory failure prior to ICU admission but had significantly lower markers of inflammation (CRP) and organ dysfunction (creatinine, LDH) compared to nonpregnant patients." (PMID 39861839, 2024). "Over the progression of the pandemic, several studies have pointed out the utility of CRP in differentiating COVID-19 patients with or without pneumonia and/or with a higher incidence of complications and worse overall prognosis." (PMID 38398280, 2024).
COVID-19 (continued). "We performed a cross-sectional study aimed to investigate the changes in circulating levels of arachidonic acid, interleukin 6 (IL-6), and C-reactive protein (CRP) in patients with FluA, RSV, or COVID-19, and to analyze the potential of these parameters as diagnosis or prognosis biomarkers." (PMID 39066228, 2024). "Given the significance of these biomarkers in the clinical management of COVID-19, this study aimed to evaluate the effects of B. coagulans Unique IS-2 and B. clausii UBBC-07 on the levels of CRP, serum ferritin, LDH, D-dimer, and IL-6 in COVID-19 patients and on recovery." (PMID 39866999, 2024). "However, we just found abnormal WBC, MCV, BUN, Cr, total bilirubin, direct bilirubin, CRP, K, CPK, increased neutrophils, and decreased lymphocytic count as indicators of COVID-19 mortality." (PMID 37117397, 2023). "CRP was additionally included in this work since it was collected as part of the TB TRIAGE+ protocol and had also been indicated as a potentially useful marker of COVID-19 prognosis." (PMID 37952026, 2023). "Additionally, for CRP-apheresis, the treatment indications realized so far are acute and life-threatening settings such as AMI, stroke or severe COVID-19." (PMID 37626775, 2023). "The interaction between CRP and SPARC may affect the immune response and viral clearance in COVID-19." (PMID 38077346, 2023). "In this study, according to the comparison between COVID positive and negative groups, there is also not a significantly higher (p=0.4691) CRP level for patients with COVID-19." (PMID 37364815, 2023). "The results indicate that, unlike other inflammatory biomarkers of COVID-19 (i.e., hsTrop, C-reactive protein, D-dimer, and ferritin), sLRP1 displays a biphasic response in COVID-19." (PMID 37168200, 2023). "Similarly, higher values of inflammatory markers such as CRP and procalcitonin were found more often in the group of children with PIMS than in COVID-19-positive patients." (PMID 37373677, 2023). "CRP proved to be one of the earliest negative prognostic markers in COVID-19 because its levels increased before the appearance of radiologic findings at chest computer tomography (CT)." (PMID 36836679, 2023). "Regarding CRP, the percentage of parameters with normal levels was similar between the four groups (both groups with COVID-19 (ward: 17.1%; ICU: 23.5%) and both groups without COVID-19 (ward: 17.3%; ICU: 26.6%)." (PMID 37510647, 2023). "In COVID-19 patients, procalcitonin (PCT) and C-reactive protein (CRP) performance in identifying bacterial infections remains unclear." (PMID 37887237, 2023). "IL-6, CRP, ferritin, LDH, and D-dimer were increased in all forms of COVID-19." (PMID 37239895, 2023). "In the subcohort of COVID-19 patients plasma chemerin did not correlate with CRP (r = 0.219, p = 0.339), procalcitonin (r = 0.112, p = 0.630) or IL-6 (r = 0.165, p = 0.475)." (PMID 37509420, 2023). "(r= 0.84, p=0.005) and CRP levels in COVID-19 patients without T2D, while the abundance of Bifidobacterium spp." (PMID 36844398, 2023). "The comparison analysis by post hoc test among the groups in this study based on the biomarkers showed that CRP, ferritin, ESR, and IL-6 are significantly changed in COVID-19 patients and could be a promising biomarker among the patients." (PMID 37363608, 2023). "CRP, for instance, has been proposed as a useful biomarker for predicting the likelihood of exacerbation in non-severe COVID-19 patients." (PMID 37396915, 2023). "Specifically, our findings on LDH, age, red blood cell distribution standard deviation, neutrophils, basophils, and C-reactive protein for severe and non-severe COVID-19 cases are supported by the results obtained across various prior investigations." (PMID 38125502, 2023). "In the COVID-19 patients, the plasma sCD137 did not correlate with CRP (r = −0.231, p = 0.289), procalcitonin (r = 0.129, p = 0.559), ferritin (r = 0.208, p = 0.341), or IL-6 (r = −0.122, p = 0.600)." (PMID 38139346, 2023).
COVID-19 (continued). "The severe COVID-19 group in our study has a significant increase in CRP with a median range of 73 mg/L compared to the non-severe group which had a median of 6.3 mg/L." (PMID 36819137, 2023). "Notably, we demonstrated the relationships between two markers that we have already described as prognostic factors in COVID-19 patients, namely NLR and CRP, with P/F, which is in turn a marker of respiratory failure secondary to respiratory distress." (PMID 37373750, 2023). "Though underpowered for a reliable confirmation of these findings, our results substantially confirmed a slightly better accuracy of MR-proADM than CRP in predicting a negative outcome in COVID-19 patients." (PMID 37371775, 2023). "Higher GGT levels were associated with lower albumin and higher CRP, ALT, and ALP levels in the 82 COVID-19 patients who did not have chronic liver disease or an alcohol history." (PMID 36747045, 2023). "In conclusion, physicians must be vigilant at all times to diagnose DKA with high degree of clinical suspicion in diabetic patients with COVID-19, especially in those with AKI, elevated CRP, hypoxic respiratory failure, need for intubation, and need for vasopressors." (PMID 37102024, 2023). "Biomarkers that are associated with predicting clinical progression and outcome in COVID-19, such as D-dimers, CRP, and IL-6, were not included in the study." (PMID 37400927, 2023). "For the COVID-19-negative patients, CRP was at 7.0 mg/L (SD = 6.7) in the CKD group and 1.7 mg/L (SD =1.6) in the healthy controls." (PMID 36983566, 2023). "In addition, it was found that COVID-19 patients experienced significant drops in HRV, indicating decreased parasympathetic activity, prior to an increase in the acute inflammatory marker C-reactive protein." (PMID 37664433, 2023). "Pre-cannulation complete blood count and arterial blood gas labs, APACHE II and SOFA scores, and other stratifying markers of COVID-19-related systemic inflammation (i.e., IL-6 and c-reactive protein) were comparable between the survivors and non-survivors." (PMID 37305142, 2023). "Even though MAFLD patients had higher CRP levels than the nonMAFLD group, in further analysis, CRP failed to reach statistical significance regarding its independent contribution to COVID-19 outcomes." (PMID 37629728, 2023). "As far as we know, there is no published data comparing CRP levels between bacterial pneumonia and COVID-19, but generally, CRP is more elevated with bacterial than viral infections." (PMID 38585537, 2023). "We hypothesize that CRP and PCT kinetics could be useful in predicting ICU-acquired infections in COVID-19 patients prior to infection diagnosis." (PMID 37834754, 2023). "While there is an association of CRP with severity in our cohort (severe vs. moderate COVID-19: 14.83 mg/dl vs. 7.53 mg/dl, p = 0.05), we did not observe a correlation between PP aggregates and the inflammatory markers CRP and Interleukin-6." (PMID 37935793, 2023). "Regarding the inflammatory markers and complete blood count, the median values of the red blood count, platelets and CRP were significantly lower in COVID-19 patients with cirrhosis compared to those without cirrhosis p < 0.05)." (PMID 37371636, 2023). "CRP level was significantly higher (P < 0.0001) in MetS cases with COVID-19 (5.7 ± 2.1 mg/L) in relation to MetS cases without COVID-19 infection (1.4 ± 0.5 mg/L)." (PMID 37142990, 2023). "The comparison of the oxidative stress marker (LDH) in COVID-19 patients revealed that the subjects with LDH values lower than 544 U/L were young male and presented lower levels of D-dimer, AST, ALT, glucose, CRP, and creatinine, as well as lower levels of leukocytes, neutrophils, NLR, and FIB-4." (PMID 36829793, 2023). "Similar results were found in patients with COVID-19 and NTIS (27.5% of the total), who were characterized by higher levels of ESR, CRP and procalcitonin, and a lower lymphocyte count than in COVID-19 non-NTIS patients." (PMID 36767756, 2023).
COVID-19 (continued). "Another study conducted in Spain suggests that a CRP value above the threshold of 9.1 mg/dl and a SOFA score higher than 2 in COVID-19 patients at the time of admission are independent predictors (with a sensitivity and specificity of 77%) of admission to the ICU." (PMID 37241099, 2023). "In both groups, IL-6 was significantly correlated with CRP (COVID-19: ρ = 0.73, p < 0.001; non-COVID-19: ρ = 0.70, p < 0.001) and leucocytes (COVID-19: ρ = 0.39, p < 0.001; non-COVID-19: ρ = 0.57, p < 0.001)." (PMID 37733154, 2023). "Recent studies have linked laboratory measures of hyperinflammation such as macrophage chemoattractant protein 1 (MCP-1), C-reactive protein (CRP) and interleukin-6 (IL-6), ferritin and procalcitonin (PCT) as strong predictors of disease severity in hospitalized patients with COVID-19." (PMID 37744227, 2023). "There was a significant difference in CRP levels–significantly higher in the COVID-19 group, but not in lymphocyte count." (PMID 36862706, 2023). "The relationship between the CRP level and patient age, obesity, and sex in COVID-19 also has not been resolved." (PMID 38003780, 2023). "C-reactive protein (CRP) levels were measured in only 41 out of 1733 individuals with COVID-19, and ferritin levels were not measured in any of them." (PMID 37941713, 2023). "The most common abnormal laboratory results in both COVID-19 survivors and non-survivors were increased values of CRP (87%), ferritin (69.9%), and D-dimer (63.8%), and reduced levels of serum CO2 (50%) and lymphocyte count (49%)." (PMID 38130539, 2023). "PSP for point-of-care use has also been described to differentiate survivors and non-survivors among ICU COVID-19 patients in reiterative measurements, in addition to CRP and PCT." (PMID 37894237, 2023). "According to the findings of chest CT scan of COVID-19 patients, it has been reported that there is no substantial correlation between hs-CRP levels and COVID-19." (PMID 37308948, 2023). "In patients with severe COVID-19 and poor outcomes, the lymphocyte, eosinophil and platelet counts decreased, whereas neutrophil, NLR, IL-6, procalcitonin, D-dimer, ferritin, amyloid A protein and CRP levels increased." (PMID 38099004, 2023). "Important imaging studies (CT scan severity score) and changes in specific biomarkers levels, especially ferritin and C-reactive protein, were also noted and should be further investigated in correlation with the pathophysiological mechanisms of AKI progression in COVID-19 patients." (PMID 37685436, 2023). "In comparison, laboratory findings and clinical parameters such as CRP, PCT, and oxygen saturation are widely available and less invasive measures that can be used to assess disease severity and guide management decisions in COVID-19 patients." (PMID 37443616, 2023). "The inflammatory markers were examined in both co-infected and non-co-infected COVID-19 hospitalised patients, including abnormal lymphocyte count, neutrophile, CRP, and D-dimer." (PMID 37630481, 2023). "The COVID-19 Mortality Prediction (CoMPred) indicator was developed by including the age and the following lab investigations: neutrophil-to-lymphocyte ratio (NLR), D-Dimer, PT, aPTT, ESR, CRP, and urea levels." (PMID 37893025, 2023). "In COVID-19, some validated scoring systems, such as the SCOPE score, which is based on biomarkers such as C-reactive protein (CRP), ferritin, D-dimer, and IL-6, demonstrated good prediction of the progression of COVID-19 pneumonia to severe respiratory failure or death within 14 days." (PMID 36675573, 2023). "In COVID-19-negative patients, the CRP was 7.0 mg/L (SD = 6.7) in the CKD group and 1.7 mg/L (SD = 1.6) in the healthy controls." (PMID 38203482, 2023). "Of note was that for six markers (CRP, ferritin, IL-6, IP-10, SAA1/A2, and S100A12) higher values were detected in COVID-19 sera whereas for ApoA1, significantly lower levels were detected in the COVID-19 group (p<0 · 0001)." (PMID 36590898, 2023).
COVID-19 (continued). "DPP3 was significantly elevated in COVID-19 patients (median 20.85 ng/ml, 95% CI 18.34–24.40 ng/ml), as opposed to those without SARS-CoV-2 (median 13.80 ng/ml, 95% CI 11.30–17.65 ng/ml; p < 0.001, AUC = 0.72), opposite to IL-6, CRP (each p = n.s)." (PMID 37733154, 2023). "In our study, CRP was significantly higher in non-survivor COVID-19 patients compared with survivor groups." (PMID 36836679, 2023). "The percentage of M-MDSCs correlated positively with neutrophil count, C-reactive protein (CRP) and D-dimer levels, hospital stay and viral RNA load and negatively with lymphocyte count and serum albumin in COVID-19 patients admitted to ICU compared to healthy controls and non-ICU patients." (PMID 36793739, 2023). "The incidence of MI at ICU admission was lower in COVID-19 patients (36.4%) compared to non-COVID-19 patients (56%), and this difference persisted after adjusting for age, sex, coronary artery disease, heart failure, SOFA score, lactate, and C-reactive protein (RR 0.84 (95% CI, 0.71–0.99))." (PMID 37835047, 2023). "The interaction between CRP and SPARC expressed by megakaryocytes may modulate the immune response and contribute to regulating viral clearance and inflammation in COVID-19 patients." (PMID 38077346, 2023). "In both the development and validation cohorts, greater CRP andferritin levels and reduced lymphocyte and eosinophil levels werefound to be statistically significant in COVID-19 patientscompared to non-COVID-19 cases." (PMID 38152003, 2023). "We found that 6 months after COVID-19 onset, the participants demonstrated significantly increased mean values for body weight, BMI, and HbA1c; a decreased mean dLDL-c level; and constant mean AST, ALT, and CRP levels." (PMID 37653091, 2023). "Nevertheless, our previous study of pediatric COVID-19 with severe pneumonia found that abnormal biomarkers such as lymphopenia and raised C-reactive protein were typically absent." (PMID 37308825, 2023). "One validated latent vector could be extracted from the three symptom domains and a composite based on CRP, KYN/TRY, and IR (Long COVID), and PBT and SpO2 (acute COVID-19)." (PMID 37333619, 2023). "There was a significant difference in lymphocyte count (1.54 ± 1.5 103/μL vs. 1.66 ± 0.7 103/μl; p = 0.04) and C-reactive protein (CRP) levels (59.4 ± 68.4 mg/L vs. 21.9 ± 40.9 mg/L; p = 0.0012) between COVID-19 and non-COVID-19 AIS patients." (PMID 36862706, 2023). "Therefore, we aimed to analyze the performance of lymphocyte count, NLR, CRP level, SARS-CoV-2–IgM antibody rapid serology test, and typical chest x-ray in predicting COVID-19 in asymptomatic individuals who underwent emergency medical procedures." (PMID 37127269, 2023). "Moreover, inflammatory markers including C-reactive protein, ferritin, interleukin (IL)-6, IP-10, MCP1, MIP1A, TNF-α, and vWF all were elevated in COVID-19 patients." (PMID 37854057, 2023). "Statistically, significantly more patients without COVID-19 had high creatinine levels (38.6 vs. 19.5), low albumin levels (79.7 vs. 58.1), and high CRP levels (96.4 vs. 83.3) versus the SARS-CoV-2-positive patients." (PMID 36838400, 2023). "In this retrospective study, we compared the prognostic value of baseline NLR, morning cortisol, ferritin, and C-reactive protein (CRP) levels among patients with severe and non-severe COVID-19." (PMID 37814623, 2023). "The findings indicated that the patients with severe symptoms had significantly higher levels of procalcitonin (PCT), interleukin-6 (IL-6), ESR, and CRP than that of the nonsevere cases of COVID-19." (PMID 37168698, 2023). "The values of CRP, LDH, and the concentration of corticosteroids administered to the investigated patients highlighted a statistical difference between the severe and moderate forms of COVID-19." (PMID 38248722, 2023).